GCGR (glucagon receptor)
Description:
G protein-coupled receptor for glucagon that plays a central role in the regulation of blood glucose levels and glucose homeostasis. Regulates the rate of hepatic glucose production by promoting glycogen hydrolysis and gluconeogenesis. Plays an important role in mediating the responses to fasting. Ligand binding causes a conformation change that triggers signaling via guanine nucleotide-binding proteins (G proteins) and modulates the activity of down-stream effectors, such as adenylate cyclase. Promotes activation of adenylate cyclase. Besides, plays a role in signaling via a phosphatidylinositol-calcium second messenger system.
Synonyms: GL-R; GGR; MVAH
Tractability: Small molecule: a drug acting on it is in phase 2 or 3 trials; a structure with a bound ligand is known; a high-quality ligand is known; it belongs to a druggable protein family. Antibody: a drug acting on it is in phase 2 or 3 trials; UniProt places it where antibodies can reach, with high confidence; its Gene Ontology location is reachable by antibodies, with high confidence; UniProt predicts a signal peptide or a membrane-spanning region. PROTAC: a small molecule that binds it is known. Other modalities: an approved drug acts on it.
Target class: Membrane receptor; Glucagon-like receptor; Family B G protein-coupled receptor; Glucagon receptor; Peptide receptor (family B GPCR)
Chemical probes: PD082185, PD083115, PD084234, PD085389, PD088664, PD088669
Gene: Protein-coding gene on chromosome 17 (81,803,105 to 81,814,023, forward strand). Ensembl gene ENSG00000215644.
Subcellular location: Cell membrane
Subcellular location (Human Protein Atlas): Golgi apparatus
Pathways (Reactome):
Signal Transduction: G alpha (q) signalling events; G alpha (s) signalling events; Glucagon-type ligand receptors
Metabolism: Glucagon signaling in metabolic regulation
Gene Ontology:
Molecular function: glucagon receptor activity; protein binding; guanyl-nucleotide exchange factor activity; peptide hormone binding; G protein-coupled receptor activity; transmembrane signaling receptor activity
Biological process: adenylate cyclase-activating G protein-coupled receptor signaling pathway; adenylate cyclase-modulating G protein-coupled receptor signaling pathway; cellular response to glucagon stimulus; cellular response to starvation; generation of precursor metabolites and energy; glucose homeostasis; positive regulation of gene expression; regulation of blood pressure; response to nutrient; response to starvation; cell surface receptor signaling pathway; G protein-coupled receptor signaling pathway
Cellular component: plasma membrane; membrane
Genetic constraint (gnomAD): Loss-of-function variants: 41 observed, 52.24 expected, observed/expected ratio (o/e) 0.78, 90% interval 0.61 to 1.02. The upper end of that interval is the gene's LOEUF score, 1.02, which puts it in group 4 of 6, group 1 being the genes least tolerant of losing a copy. Missense variants: 595 observed, 619.89 expected, observed/expected ratio (o/e) 0.96, 90% interval 0.9 to 1.03. Synonymous variants: 278 observed, 257.76 expected, observed/expected ratio (o/e) 1.08, 90% interval 0.98 to 1.19.
Homologues: Orthologues: chimpanzee GCGR (97% identical), macaque GCGR (93% identical), mouse Gcgr (82% identical), guinea pig GCGR (81% identical), pig GCGR (81% identical), rat Gcgr (81% identical), dog GCGR (79% identical), tropical clawed frog gcgr (54% identical), zebrafish gipr (47% identical). Paralogues in human: GIPR (48% identical), GLP1R (45% identical), GLP2R (40% identical), SCTR (35% identical), VIPR1 (34% identical), ADCYAP1R1 (32% identical), VIPR2 (31% identical), PTH1R (31% identical), PTH2R (29% identical), GHRHR (29% identical), CALCRL (25% identical), CALCR (24% identical), and 30 more.
Diseases named in the same sentence as GCGR in open-access papers:
GCGR is named in the same sentence as 79 diseases in open-access papers, as found by Europe PMC text mining. Sharing a sentence is not in itself a finding about the gene and the disease. The quoted sentences say what the papers report.
Obesity (72 papers, 2012 to 2026). Accumulation of substantial excess body fat. "Survodutide is a novel GCG/GLP-1 receptor (GCGR/GLP-1R) dual agonist in clinical development for people with obesity and people with metabolic dysfunction-associated steatohepatitis (MASH)." (PMID 41638399, 2026). "We sought to investigate the direct effects of glucagon receptor activation in a clinically relevant model of obesity-associated hyperglycaemia, using a peptide agonist which was over ten times more potent at the glucagon than the GLP-1 receptor." (PMID 38677509, 2024). "Mazdutide (also known as IBI362 or LY3305677), a novel once-weekly glucagon-like peptide-1 (GLP-1) and glucagon receptor dual agonist, achieved 12-week body weight loss up to 6.4% at doses up to 6 mg in Chinese adults with overweight or obesity." (PMID 36247927, 2022). "When administered exogenously, OXM can improve glucose tolerance and result in body weight loss, making GLP-1 and glucagon receptor dual agonists a promising treatment option for patients with T2D and/or obesity." (PMID 35750681, 2022). "With balanced GLP-1 receptor and glucagon receptor agonism, mazdutide demonstrated promising efficacy on body weight loss in Chinese adults with overweight or obesity." (PMID 36247927, 2022). "When administered exogenously, OXM can improve glucose tolerance and result in weight loss, making GLP-1 receptor and glucagon receptor dual agonists a new promising treatment option for patients with diabetes and/or obesity." (PMID 34430840, 2021). "Glucagon-like peptide-1 and glucagon receptor (GLP-1R/GCGR) co-agonism can maximise weight loss and improve glycaemic control in type 2 diabetes and obesity." (PMID 33933675, 2021). "Firstly, GCGR agonism rapidly activates energy expenditure in adult humans, and it increases thermogenic capacity and metabolic rate to drive weight loss in preclinical models of obesity." (PMID 35547006, 2022). "Central KLB in diet-induced obesity and GCGR-mediated weight loss." (PMID 33411693, 2021). "Thus, therapeutics stimulating glucagon receptor (GCGR) signaling are promising for obesity treatment; however, the underlying mechanism(s) have yet to be fully elucidated." (PMID 33411693, 2021). "Therefore, glucagon receptor agonists could be an effective therapeutic strategy against obesity and T2D that are risk factors for AD development." (PMID 38977507, 2024). "The article herein discusses the key attributes of GCGR activation to promote and possibly maintain body weight loss, highlighting key mechanisms of GCGR agonism that make it an attractive partner for pairing with other therapeutic approaches in the complex treatment of obesity." (PMID 35547006, 2022). "Furthermore, chronic exposure to glucagon receptor agonists may improve the reproductive hormone status of men with obesity-related hypogonadism because weight loss itself can ameliorate hypothalamic hypogonadism in obese men." (PMID 32232363, 2020). "For example, activation of glucagon family receptors (GLP1R, GIPR, GCGR) shows therapeutic efficacy in treating type-2 diabetes and obesity; however, these receptors are expressed in multiple tissues." (PMID 41264544, 2025). "A new generation of anti-obesity medications (AOM), the Glucagon-like peptide-1 (GLP-1) / Gastric inhibitory polypeptide (GIP) / Glucagon receptor agonists, lead to 15–20% weight loss and are transforming the clinical care of people with obesity." (PMID 39149290, 2025). "In fact, glucagon receptor agonism has been shown to possess significant anti-obesity effects, as evidenced by its strong reduction in food intake and increase in systemic energy expenditure." (PMID 41515247, 2025). "In prior phase II trials, survodutide (BI 456906), a once-weekly dual GLP-1R/GCGR agonist, has shown significant efficacy in reducing body weight and hyperglycemia in individuals with obesity and/or T2DM." (PMID 40004572, 2025).
Obesity (continued). "Mazdutide is a dual GLP-1 and glucagon receptor agonist under development for treating obesity and diabetes." (PMID 40104296, 2025). "GCGR knockout mice show reduced adipose mass and resistance to diet-induced obesity through enhanced lipolysis and fatty acid oxidation." (PMID 41012812, 2025). "Recently, a superior efficacy of dual GLP-1R/GCGR agonism versus single GLP-1 agonism in reducing obesity in mice has been attributed to a remodelling of WAT towards browning and UCP-1-dependent BAT activation." (PMID 40892365, 2025). "We also provide evidence of the utility of GCGR-preferring peptide analogues for the recovery of obesity-induced dysglycaemia." (PMID 38677509, 2024). "Several peptide dual agonists of the human glucagon receptor (GCGR) and the glucagon-like peptide-1 receptor (GLP-1R) are in development for the treatment of type 2 diabetes, obesity and their associated complications." (PMID 38755312, 2024). "In rats fed a high-fat diet, a logically constructed GLP-1 and glucagon receptor bifunctional agonist successfully restored glucose tolerance and reduced obesity." (PMID 38255264, 2024). "Recently, several trials have included multi-targeting agonists of GLP-1R, GIPR, or glucagon receptor (GCGR) for the treatment of both T2D and obesity." (PMID 38850440, 2024). "Recently, it has been shown that glucagon receptor agonists are effective in the treatment of obesity and T2D by increasing energy expenditure and inhibiting food intake, despite their hyperglycaemic effects (Novikoff and Müller 2023)." (PMID 38977507, 2024). "Researchers interested in this direction can see more details on the efficacy of GLP-1R/GCGR agonists in the treatment of obesity in Sanchez-Garrido’s review." (PMID 36843578, 2023). "In conclusion, developing GCGR agonists, particularly unimolecular dual and multi‐agonists, represents a promising avenue for addressing obesity, diabetes and metabolic disorders." (PMID 38093651, 2023). "Together, these data provide further evidence that peptidic GCGR antagonists are effective treatment options for obesity-driven forms of diabetes, even when accompanied by insulin deficiency." (PMID 36005280, 2022). "Several multi-targeting agonists at GIPR, GLP-1R or GCGR, developed to maximize metabolic benefits with reduced side-effects, are in clinical trials to treat type 2 diabetes and obesity." (PMID 35217653, 2022). "GCGR plays an important role in regulating blood glucose levels and thus represents a therapeutic potential for obesity and type 2 diabetes therapies." (PMID 36552350, 2022). "In that respect, GCGR KO mice are reported to be resistant to high-fat feeding-induced obesity, but the possibility for life-long adaptations in these animals should not be overlooked." (PMID 36005280, 2022). "Here, we describe the discovery and characterization of BI 456906, a once-weekly, injectable GCGR/GLP-1R dual agonist currently in Phase II clinical development for obesity, type 2 diabetes, and NASH." (PMID 36356832, 2022). "In animal models of obesity, administration of dual GLP‐1R/GCGR agonists resulted in superior weight loss, lower glucose levels, and reduced food intake compared with pure GLP‐1R agonists alone." (PMID 34713962, 2022). "Delineating the relative contribution of GcgR agonism to the efficacy of triple GLP-1R/GIPR/GcgR agonists remains a critical question in the field of obesity pharmacology." (PMID 35809773, 2022). "SAR425899, a once-weekly GLP-1 and glucagon receptor dual agonist, achieved placebo-adjusted mean HbA1c level reductions up to 0.75% in patients with overweight or obesity and T2D11." (PMID 35750681, 2022). "BI 456906 is a potent GCGR/GLP-1R dual agonist with robust anti-obesity efficacy achieved by increasing energy expenditure and decreasing food intake." (PMID 36356832, 2022).
Obesity (continued). "In summary, the current study establishes that peptide-based GCGR antagonism exerts notable benefits in obesity-driven forms of diabetes, even in the presence of insulin deficiency." (PMID 36005280, 2022). "Based on the accumulation of such findings, we propose that the thermogenic activity of GCGR agonism will also complement other anti-obesity agents that lower body weight by suppressing appetite." (PMID 35547006, 2022). "Weighing the therapeutic potential of triple agonists for diabetes and obesity against the cardiovascular effects of GcgR agonism specifically is a necessary consideration." (PMID 35809773, 2022). "This 12-week randomised, placebo-controlled phase 1b study evaluated the safety, tolerability, pharmacokinetics and efficacy of IBI362, a novel weekly-dose GLP-1 and glucagon receptor dual agonist, in Chinese adults with overweight or obesity." (PMID 34430840, 2021). "IBI362 (LY3305677) is a novel weekly-dose glucagon-like peptide-1 and glucagon receptor dual agonist being developed for the treatment of obesity and type 2 diabetes." (PMID 34430840, 2021). "Together, these data suggest GCGR agonism mediates part of its weight loss properties through central KLB and has implications for future treatments of obesity and metabolic syndrome." (PMID 33411693, 2021). "Glucagon increases energy expenditure; consequently, glucagon receptor agonists are in development for the treatment of obesity." (PMID 32232363, 2020). "Our finding that glucagon administration does not affect reproductive hormones in healthy men provides important data on potential off-target effects in the ongoing development of glucagon receptor agonists for the treatment of obesity." (PMID 32232363, 2020). "In support of this concept, antagonising glucagon receptor (GCGR) signalling can improve insulin sensitivity in experimental models of diabetes and obesity." (PMID 30626440, 2019). "Considering the beneficial effects of GcgR antagonists on glycaemia, it would seem counterintuitive to employ agonism in a therapy for obesity and, certainly, diabetes." (PMID 28733905, 2017). "Dual agonism of GLP-1R/GCGR and very recently triagonism with GLP-1R/GIPR/GCGR have been found to have potent effects to reverse obesity in rodents." (PMID 28223965, 2017). "Glucagon receptor antagonists and humanized glucagon antibodies are currently studied as promising therapies for obesity and type II diabetes." (PMID 26909312, 2015). "It was reported that absence of glucagon signaling was associated with decreased body weight and food intake in GCGR knockout (Gcgr−/−) mice when HFD was challenged, implying a protective role of glucagon antagonists as anti-obesity agents." (PMID 23226550, 2012). "Pemvidutide is an investigational dual GLP-1/glucagon receptor agonist targeting obesity and MASH." (PMID 40104296, 2025). "Recent data on individuals living with overweight and obesity treated with the GLP-1R/GCGR co-agonist SAR425899 indicated that such individuals exhibit a smaller-than-expected decrease in the sleeping metabolic rate, increased fat oxidation but no overt induction of energy expenditure." (PMID 40892365, 2025). "Further research is needed to ascertain whether the GCGR agonism present in multi-receptors anti-obesity drugs under development retains these effects of single GCGR agonism." (PMID 40892365, 2025). "Our finding may also provide an explanation for the therapeutic benefits of glucagon receptor agonists for individuals with obesity and type 2 diabetes reported recently in clinical trials." (PMID 40454488, 2025). "Another unimolecular once-weekly dual GLP-1R/GCGR agonist is efinopegdutide (MK-6024), which was able to prove significant reductions in body weight compared to placebo, but no reductions of the HbA1c levels, when investigated in people with obesity and T2DM." (PMID 40004572, 2025).
Obesity (continued). "While data from these trials demonstrate improved efficacy in obesity and T2D through the addition of GCGR agonism to GLP-1R/GIPR agonism, whether these synergistic improvements are evident in kidney-related outcomes remains to be determined." (PMID 38477666, 2024). "We then examined whether glucagon receptor agonist therapy in the setting of obesity-induced dysglycaemia directly restores islet β-cell functional connectivity." (PMID 38677509, 2024). "Research on obese mice suggests that unimolecular poly-pharmacology is an effective means to deal with various mechanisms leading to obesity and further indicates that GCGR activation is the distinguishing factor between single or double agonists and triple agonists of incretin receptors." (PMID 36843578, 2023). "In addition, the potential use of co-agonist molecules with an affinity for GLP-1 and the glucagon receptor is also under investigation for obesity and T2D treatment." (PMID 37233628, 2023). "Several GLP-1 and glucagon receptor dual agonists, including cotadutide, SAR425899, JNJ-64565111 and mazdutide, showed overall favourable safety profiles and varying body weight loss efficacy in individuals with overweight or obesity." (PMID 36247927, 2022). "Thus, it is anticipated that GCGR activation may become a trail blazer in the field of thermogenic therapeutics, not only enhancing the weight loss profile of current therapies, but also that of other anti-obesity medications that function by reducing daily caloric intake." (PMID 35547006, 2022). "In preclinical studies, the glucagon-GCGR system affects key metabolically relevant organs (including the liver and white and brown adipose tissue) to boost whole-body thermogenic capacity and protect from obesity." (PMID 35547006, 2022). "Therefore, this HFF-STZ murine model represents an ideal tool to fully explore the positive effects of peptide-based GCGR antagonists in obesity-driven forms of diabetes, where restoration of functional beta-cell mass would be highly advantageous." (PMID 36005280, 2022). "The importance of the liver in mediating the anti-obesity action of glucagon administration is exemplified by findings in liver-specific knockout models, where the absence of the GCGR ablates the ability of glucagon to induce weight loss." (PMID 35547006, 2022). "These pre-clinical data suggest unimolecular poly-pharmacology as an effective means to target multiple mechanisms contributing to obesity and further implicate GcgR activation as the differentiating factor between incretin receptor mono- or dual-agonists and triagonists." (PMID 35809773, 2022). "JNJ-64565111, a once-weekly GLP-1 and glucagon receptor dual agonist, showed encouraging weight loss but no improvement in glycaemic parameters in adults with type 2 diabetes and obesity." (PMID 34430840, 2021). "Detailed mechanistic research is also needed to establish the relative contributions of G protein- and β-arrestin-mediated effects at both GLP-1R and GCGR and will help clarify how investigational incretin receptor agonists are prioritised during drug development for T2D and obesity." (PMID 33933675, 2021). "GLP-1R/GCGR co-agonists may hold advantages over GLP-1R mono-agonists for treating obesity and related metabolic diseases as their GCGR-mediated effects on energy expenditure can promote additional weight loss." (PMID 33933675, 2021). "Because glucagon receptor agonists are being developed to treat obesity, which is frequently complicated by MOSH, it is important to conclusively determine whether glucagon receptor agonism can directly modulate the reproductive axis in men." (PMID 32232363, 2020). "Indeed, glucagon receptor antagonists and humanized glucagon antibodies appear to be promising therapies for obesity and type II diabetes in preclinical trials." (PMID 26909312, 2015).